METTL3 (methyltransferase 3, N6-adenosine-methyltransferase complex catalytic subunit)
Diseases named in the same sentence as METTL3 in open-access papers (continued):
Sharing a sentence is not in itself a finding about the gene and the disease.
endometriosis (continued). "Histopathological assessments of endometriosis patients have indicated a notably lower m6A modification level in endometrial tissues than in healthy control tissues, a finding that may be correlated with the decreased expression of METTL3." (PMID 40356909, 2025). "For example, knockdown of the methyltransferase METTL3 has been observed to promote migration and invasion of human embryonic stem cell (hESC), whereas cell migration and invasion are enhanced by downregulation of METTL3 to promote the development of endometriosis." (PMID 38572667, 2024). "Regarding its role in endometriosis, studies have found that patients with endometriosis have lower levels of m6A in the endometrium than individuals with normal endometrium and that the expression levels of METTL3 and METTL14 are downregulated in ectopic endometria compared with eutopic endometria." (PMID 39831202, 2024). "Finally, we found that m6A alterations might be one of the important reasons for the progression of endometriosis, especially with significant downregulation of the expressions of METTL3 and YTHDF2." (PMID 36675186, 2023). "Our study establishes METTL3-YTHDF2-SIRT1/FOXO3a as a critical axis and potential mechanism in endometriosis." (PMID 37353804, 2023). "Specifically, suppressive METTL3 enhances cell migration and invasion by attenuating DGCR8-mediated maturation of pri-miR126 in an m6A-dependent manner, thus contributing to endometriosis development." (PMID 35813486, 2022). "This research has demonstrated that some m6A regulators, such as METTL3, FTO, and IGF2BP2, participate in the process and development of endometriosis, while there are few studies on other m6A regulators." (PMID 36672827, 2022). "Endometriosis patients with a high expression of CBLL1 and METTL3 showed a notably high expression level of ALKBH5." (PMID 36672827, 2022). "METTL3-dependent m6A is engaged in the maturation of primary microRNA126 mediated by DGCR8, which further increased the migration and invasion of endometrial stromal cells in endometriosis." (PMID 37270544, 2023). "Endometriosis patients at stages III + IV (according to the revised American Fertility Society classification, r-AFS) or without deeply infiltrating endometriosis and cyst size ≥ 3 cm in diameter showed reduced METTL3 expression." (PMID 37353804, 2023). "Furthermore, they concluded that METTL3 downregulation inhibited the maturation of pri-miRNA126 to miRNA126 via DGCR8, thereby enhancing the migration and invasion of endometrial stromal cells and leading to the development of endometriosis." (PMID 36894952, 2023).
periodontitis (15 papers, 2021 to 2025). An acute or chronic inflammatory process that affects the tissues that surround and support the teeth. "In periodontitis mice, METTL3 inhibitor SAH promoted alveolar bone loss and local inflammatory status, which were partially rescued by Wnt/β-catenin pathway activator CHIR-99021 HCl." (PMID 38267969, 2024). "Our study unveils a previously unknown pathogenic mechanism for periodontitis and indicates METTL3 as a potential therapeutic target, which may shed light on the clinical treatment of inflammatory diseases." (PMID 38696610, 2024). "The study unveils a previously unknown pathogenic mechanism of METTL3‐mediated m6A modifications in periodontitis and indicates METTL3 as a potential therapeutic target." (PMID 38696610, 2024). "For instance, METTL3 played a crucial role in promoting ribosome biogenesis and oxidative phosphorylation in osteoblasts by activating the Wnt/β-catenin/c-Myc signaling pathway, which helped mitigate periodontitis inflammation and additional alveolar bone loss." (PMID 40825668, 2025). "The CCK-8 assay outcomes indicated that silencing METTL3 in LOR-overexpressing cells partially negated the increase in cell viability observed with LOR overexpression in the LPS-induced periodontitis model." (PMID 40825668, 2025). "Our study provides novel insight into the anti-inflammatory potential of METTL3 in HPLFs, emphasizing the need for further investigation into the cell-specific regulatory networks that govern m6A dynamics in periodontitis." (PMID 40825668, 2025). "The ELISA results revealed that silencing METTL3 in LOR-overexpressing cells partially reversed the cytokine reduction induced by LOR overexpression in the LPS-induced periodontitis model." (PMID 40825668, 2025). "Despite significant advances in understanding the pathogenesis of periodontitis, the role of RNA modifications, particularly METTL3-mediated m6A methylation, remains underexplored." (PMID 40825668, 2025). "N6‐adenosine‐methyltransferase‐like 3 (METTL3) mediated m6A modification plays a pivotal role in periodontitis." (PMID 38696610, 2024). "Accordingly, METTL3 inhibitor promoted local inflammatory osteolysis in periodontitis mice, while Wnt signaling activator CHIR partially reversed the effect of SAH." (PMID 38267969, 2024). "Furtherly, Coptisine chloride, a natural small‐molecule, is discovered as a novel METTL3 inhibitor and performs therapeutic effect on periodontitis." (PMID 38696610, 2024). "METTL3 activated Wnt/β-catenin/c-Myc axis to facilitate ribosome biogenesis and translation rate, which influenced osteoblast function in periodontitis." (PMID 38267969, 2024). "We further identify a selective natural small‐molecule inhibitor of METTL3, which displays promising therapeutic effects on periodontitis." (PMID 38696610, 2024). "This study aims to investigate the role of METTL3 in osteoblast ribosome biogenesis in periodontitis progression." (PMID 38267969, 2024). "This study aimed to clarify the role of m6A methyltransferase METTL3 in osteoblast biology process in periodontitis and explore its potential mechanism." (PMID 38267969, 2024). "This study aimed to investigate the specific regulatory role of METTL3 in ribosomal function in LPS-stimulated osteoblasts and explore the effect of METTL3 inhibitor in periodontitis mice." (PMID 38267969, 2024). "In this study, we generate a murine periodontitis model by conditionally deleting Mettl3 in periodontal mesenchymal cells." (PMID 38696610, 2024). "In this study, we examined the role and mechanisms of METTL3 in periodontitis." (PMID 40825668, 2025). "Furthermore, coptisine chloride, a natural small molecule, was discovered to be a novel METTL3 inhibitor and has a therapeutic effect on periodontitis." (PMID 40829428, 2025). "Furthermore, METTL3 expression was reduced in periodontitis clinical tissues and positively correlated with LOR expression." (PMID 40825668, 2025).
periodontitis (continued). "Emerging evidence suggests that METTL3 may participate in periodontitis pathogenesis by modulating the inflammatory microenvironment." (PMID 40825668, 2025). "Clinically, our findings propose that enhancing the METTL3-LOR axis might offer a promising therapeutic approach for periodontitis." (PMID 40825668, 2025). "Therefore, further in vivo studies, LPS-induced periodontitis model in mice, are necessary to validate the protective role of METTL3 and LOR under physiologically relevant conditions." (PMID 40825668, 2025). "Moreover, silencing METTL3 partially negated the protective effects of LOR overexpression in LPS-induced periodontitis cell model." (PMID 40825668, 2025). "BBR and its analogs are METTL3 inhibitors that alleviate periodontitis by inhibiting pyroptosis." (PMID 40829428, 2025). "METTL3 promoted ribosome biogenesis and oxidative phosphorylation by activating Wnt/β-catenin/c-Myc signaling in LPS-treated osteoblasts and alleviated the inflammatory alveolar bone destruction in periodontitis mice." (PMID 38267969, 2024). "In order to investigate the underlying mechanism of METTL3-mediated osteoblast activity in periodontitis, RNA-seq was performed in the present study and data showed that the genes of ribosome and cytoplasmic translation were downregulated in METTL3 knockdown osteoblasts after LPS treatment." (PMID 38267969, 2024). "Here we identified METTL3 as a regulator of NLRP3 inflammasome activation in periodontitis." (PMID 38696610, 2024). "Therefore, we will further conduct animal experiments to explore the regulatory effect of METTL3 on osteogenic differentiation in the periodontitis microenvironment." (PMID 38283119, 2024). "To explore whether METTL3 is a potential therapeutic target for periodontitis, we sought to discover a small molecule inhibitor targeting METTL3 methyltransferase activity." (PMID 38696610, 2024). "In periodontitis models, knocking out Tnfaip3 offset the protective effect of Mettl3 depletion." (PMID 38696610, 2024). "Mettl3 depletion significantly decreased periodontal lesions and ameliorated local gingival inflammation, indicating the regulatory role of m6A modification in periodontitis." (PMID 38696610, 2024). "Our objective was to investigate the mechanism by which METTL3-mediated N6-methyladenosine modification regulates the osteogenic differentiation through lncRNA in periodontal mesenchymal stem cells in patients with periodontitis (pPDLSCs)." (PMID 38283119, 2024). "In addition, METTL3 knockdown in LPS-stimulated periodontitis cells reduces IL-6 and IL-8 production." (PMID 36555481, 2022). "The results of this study supplement the evidence showing that lncRNA and mRNA m6A modification regulates the osteogenic differentiation of PDLSCs and reveal the effects of METTL3 on pPDLSCs, thereby providing a reference for orthodontic treatment of periodontitis patients, to a certain extent." (PMID 36483682, 2022). "Moreover, METTL3 knockdown in LPS-stimulated periodontitis cells showed a reduced level of expression of the inflammatory cytokines, i.e., IL-6 and IL-8." (PMID 36555481, 2022). "We then conducted in vitro experiments to investigate the interaction between METTL3 and LOR in periodontitis." (PMID 40825668, 2025). "On one hand, patients suffered from periodontitis had a low expression of FOXO1 and the combination of FOXO1 to METTL3 regulates PDLSCs to promote osteogenesis through the PI3K/AKT signaling pathway." (PMID 39974190, 2025). "We specifically explored the interactions between METTL3 and Loricrin (LOR), a gene identified through bioinformatics analysis as a downregulated gene in periodontitis." (PMID 40825668, 2025). "This novel protective pathway involving METTL3-mediated m6A modification of LOR provides new insights into both the basic molecular pathology and clinical management of periodontitis." (PMID 40825668, 2025). "However, whether METTL3-mediated m6A regulates the development of periodontitis remains unknown." (PMID 38267969, 2024).
periodontitis (continued). "This is in keeping with prior research, which found that LPS-stimulated periodontitis cells, microglia cells and an IL-1β-stimulated ATDC5 chondroprogenitor cell line dramatically enhance METTL3 expression and m6A levels." (PMID 36555481, 2022). "In conclusion, we identified that METTL3-mediated m6A modification stabilizes LOR mRNA, which in turn suppresses inflammatory cytokine production, preserves fibroblast proliferation, and inhibits apoptosis in the context of periodontitis." (PMID 40825668, 2025). "Furthermore, we explored a selective small‐molecule inhibitor of METTL3 and verified its inhibitory capacity on NLRP3‐mediated pyroptosis and periodontitis." (PMID 38696610, 2024). "Another study reported that METTL3 promoted osteogenic differentiation of human periodontal ligament stem cells in an inflammatory niche by enhancing miR-141-3p levels through m6A modification, which suppressed ZEB1 and helped counteract periodontitis-induced osteogenic impairment." (PMID 40825668, 2025). "All erasers had significant expression alterations, while some of the readers did not change significantly, and the well‐studied writer protein METTL3 did not change significantly which suggests that it might not play an important role in periodontitis." (PMID 33724691, 2021). "Furthermore, METTL3 has been shown to enhance osteogenic differentiation in periodontal mesenchymal stem cells by modulating lncRNA CUTALP, which inhibited miR-30b-3p and activated Runx2, contributing to better osteogenesis and potentially alleviating periodontitis progression." (PMID 40825668, 2025).
neuroblastoma (14 papers, 2020 to 2025). Neuroblastoma (NB) is the most common solid, extracranial childhood tumor. "Polymorphisms in METTL14 gene and METTL3 gene (m6A methyltransferases) were also reported to be associated with predisposition to neuroblastoma." (PMID 34897032, 2021). "In the present study, we performed this first epidemiology study to determine the correlation of METTL3 gene polymorphisms and neuroblastoma risk in a Chinese population." (PMID 32615646, 2020). "In the current nine‐centre case‐control study, we aimed to analyse the association between the METTL3 gene single nucleotide polymorphisms (SNPs) and neuroblastoma susceptibility." (PMID 32615646, 2020). "To identify METTL3 genetic variations that confer susceptibility to neuroblastoma, we performed this multi‐centre epidemiology study." (PMID 32615646, 2020). "Collectively, we elucidated the predisposing role of METTL3 gene SNPs to neuroblastoma risk." (PMID 32615646, 2020). "In this large Chinese case‐control study, we investigated whether genetic variations in the METTL3 gene contribute to neuroblastoma risk." (PMID 32615646, 2020). "To confirm that the changes in gene expression observed in neuroblastoma cells treated with STM2457 were due to targeting METTL3, we analyzed CHGA and NTRK1 mRNA levels in control SK-N-BE2 cells and cells engineered to overexpress METTL3." (PMID 38691450, 2024). "METTL3 inhibitor treatment suppressed neuroblastoma growth and increased differentiation, supporting the potential of this therapeutic strategy for neuroblastoma." (PMID 38691450, 2024). "Despite these limitations, our studies support the potential for METTL3/14 inhibition as a therapeutic strategy for neuroblastoma." (PMID 38691450, 2024). "We also show that the changes in gene expression mediated by the METTL3 inhibitor are prognostic of survival in patients with neuroblastoma." (PMID 38691450, 2024). "METTL3 knockdown or pharmacologic inhibition of the METTL3/14 complex with STM2457 decreased the proliferation of a panel of adrenergic neuroblastoma cells, including cells that harbored amplification of the MYCN oncogene." (PMID 38691450, 2024). "Although the results of our study support the potential of METTL3 as a therapeutic target in neuroblastoma, there are limitations." (PMID 38691450, 2024). "Together, these results support the potential of METTL3/METTL14 complex inhibition as a therapeutic strategy against neuroblastoma." (PMID 38691450, 2024). "We show that small interfering RNA (siRNA)-mediated METTL3 knockdown or STM2457 treatment decreased the viability of adrenergic neuroblastoma cells and promoted differentiation." (PMID 38691450, 2024). "Pharmacological inhibition of METTL3/14 promoted neuroblastoma differentiation and suppressed tumor xenograft growth." (PMID 38691450, 2024). "We next sought to investigate the mechanisms underlying the increase in expression of targets transcripts with METTL3/14 inhibition observed in neuroblastoma cells." (PMID 38691450, 2024). "Collectively, our results show that m6A RNA modifications play a critical role in regulating the expression of METTL3-target transcripts, neuroblastoma phenotype, and tumor growth." (PMID 38691450, 2024). "Here, we show that METTL3 knockdown or pharmacologic inhibition with the small molecule STM2457 leads to reduced neuroblastoma cell proliferation and increased differentiation." (PMID 38691450, 2024). "Another limitation is that the effects of pharmacologic inhibition of METTL3/14 were analyzed in neuroblastoma cell lines and subcutaneous neuroblastoma xenograft models." (PMID 38691450, 2024). "METTL3 protein was not completely knocked down in neuroblastoma cells by either of the two METTL3 siRNAs tested, and only modest reductions in global m6A levels were observed in the METTL3 knockdown neuroblastoma cells." (PMID 38691450, 2024).
neuroblastoma (continued). "STM2457 treatment also increased the level of cleaved PARP protein in SK-N-BE2 cells, indicating that METTL3 inhibition induces apoptosis in neuroblastoma cells." (PMID 38691450, 2024). "PRMT5 has recently been shown to control intron retention of METTL3 in blastic plasmacytoid dendritic cell neoplasm, similar to our observations in neuroblastoma." (PMID 39313128, 2024). "To explore the effects of METTL3 and ALKBH5 on ADAMTS9-AS2 upregulation in neuroblastoma cells, we knocked down the expression of METTL3 in SK-N-SH cells and knocked down ALKBH5 in SK-N-Be2 cells." (PMID 37991019, 2023). "Therefore, functional genetic variants in the METTL3 gene may contribute to neuroblastoma risk." (PMID 32615646, 2020). "Our results suggest that targeting METTL3 and other RNA modifying enzymes may have therapeutic potential in neuroblastoma." (PMID 38691450, 2024). "Further, METTL3 knockdown affected gene expression in neuroblastoma cells, with up-regulated genes showing enrichment for pathways involved in neuronal differentiation such as axon development and axonogenesis, detected by RNA sequencing Gene Ontology Biological Pathway (GOBP) analysis." (PMID 38691450, 2024). "However, little is known about the m6A epitranscriptome or the role of the METTL3/METTL14 complex in neuroblastoma, a common pediatric cancer." (PMID 38691450, 2024). "METTL3/14 inhibition also led to changes in gene expression in neuroblastoma cell lines." (PMID 38691450, 2024). "This indicates that METTL3 inhibitors might be a promising therapeutic approach in ALT+ neuroblastoma treatment." (PMID 38891878, 2024). "It is possible that genetic knockout of METTL3 using CRISPR technology may promote neuroblastoma differentiation and other alterations in the cell phenotype that more closely mirror the changes observed in cells treated with the METTL3 inhibitor." (PMID 38691450, 2024). "We also validated METTL3 and ALKBH5 binding to ADAMTS9-AS2 in neuroblastoma cells using RIP followed by qRT-PCR and pulldown assays coupled with Western blotting." (PMID 37991019, 2023). "The endogenous expressions of METTL3 and ALKBH5 of the neuroblastoma cell lines regulated the m6A modification in ADAMTS9-AS2, thus affecting its RNA stability and its downstream MYCN expression." (PMID 37991019, 2023). "The endogenous expressions of METTL3 and ALKBH5 in the neuroblastoma cell lines were analyzed; the results showed that ALKBH5 expression was lowest and that METTL3 expression was highest in the SK-N-SH cells." (PMID 37991019, 2023). "Recently, METTL3-driven RNA modification at the N6 position of internal adenosine (m6A) in TERRA, a telomere-derived lncRNA, was shown to be essential in telomere maintenance in ALT+ neuroblastoma cells." (PMID 38891878, 2024). "METTL3 and METTL14 protein levels were analyzed across the 11 human neuroblastoma cell lines." (PMID 38691450, 2024). "The METTL3 small molecule inhibitor STM2457 targets m6A modification, down‐regulates MYCN expression and inhibits tumour proliferation, providing a new therapeutic strategy for MYCN‐amplified neuroblastoma." (PMID 39135292, 2024). "Since transcripts marked with m6A in control neuroblastoma cells showed increased expression in cells treated with STM2457, we hypothesized that the reduction of m6A RNA deposition resulting from METTL3/14 inhibition would enhance the stability of these transcripts." (PMID 38691450, 2024). "In two clinically annotated neuroblastoma cohorts (SEQC-NB [n = 498] and Westermann [n = 105]), superior EFS and OS were observed among patients with tumors with high METTL3 inhibitor response signature scores compared to those with low scores." (PMID 38691450, 2024).